PRL (prolactin)
Diseases named in the same sentence as PRL in open-access papers (continued):
Sharing a sentence is not in itself a finding about the gene and the disease.
metabolic disease (36 papers, 2011 to 2026). A congenital disorder (due to inherited enzyme abnormality) or acquired (due to failure of a metabolically important organ) disorder resulting from an abnormal metabolic process. "Findings of the present review highlighted that both low and high PRL levels are associated with metabolic disorders and development of MetS as consistence with other studies." (PMID 39663784, 2024). "PRL levels ~40 mcg/L were associated with lower prevalence of metabolic disease while PRL levels higher than 100 mcg/L were associated with deleterious metabolic alterations." (PMID 36704037, 2022). "Though it is clear that high prolactin levels are metabolically unfavorable, multiple studies have also shown low prolactin levels to be associated with increased metabolic disease." (PMID 36246929, 2022). "The association between low PRL levels and higher prevalence of metabolic diseases also stands for postmenopausal women and middle-aged and elderly men, implying its independence from gonadal status." (PMID 36213259, 2022). "This definition is based on multiple experimental and clinical studies showing that PRL values that are not only below but also above this level are associated with metabolic disease." (PMID 33746901, 2021). "Smoking is a known risk factor for cardiovascular disease and metabolic disorders, and our results suggest that this may be partially mediated by its effects on prolactin levels." (PMID 38826895, 2024). "Elevated prolactin levels are widely associated with worsening metabolic disease, but it appears that low prolactin levels could also be metabolically unfavorable." (PMID 36246929, 2022). "In humans, low PRL levels associate with increased prevalence of metabolic diseases." (PMID 36213259, 2022). "Another metabolic disease associated with low PRL levels is NAFLD." (PMID 36213259, 2022). "Moderately high PRL serum levels associate with lower incidence of metabolic disease." (PMID 36213259, 2022). "However, large cohort clinical studies have recently shown that low circulating PRL levels are associated with metabolic disease, whereas high PRL levels acts on the pancreas, liver, adipose tissue, and hypothalamus to maintain and promote metabolic homeostasis." (PMID 40894210, 2025). "In humans, low PRL levels have been associated with an increased prevalence of various metabolic diseases, whereas overweight and obese patients, who showed increased PRL levels, also revealed better metabolic profiles than BMI-matched patients with lower PRL values." (PMID 39857650, 2024). "Various preclinical studies highlighted that moderately elevated PRL level has a beneficial role against metabolic disorders." (PMID 39663784, 2024). "PRL improves metabolic homeostasis, and defect in PRL/PRLRs axis induce metabolic disorders and systematic complications." (PMID 39663784, 2024). "This systematic review is, to our knowledge, the first to examine PRL levels in pregnancy and the postpartum period in women with pre-existing metabolic disease (T1DM, T2DM, and PCOS)." (PMID 36769162, 2023). "The hormone prolactin (PRL) is an important milk component with protective effects against metabolic diseases." (PMID 37571383, 2023). "Recent studies also suggested an important role of PRL in metabolic disease, and PRL was proven to be a protective factor against the existence and progress of NAFLD, which were supported by our current data." (PMID 31775658, 2019). "Serum metabolome analyses could also help identify relationships between microbiome functionality and host factors such as hormonal levels (i.e., estrogens, cortisol, progesterone, prolactin), or metabolic disorders in cattle." (PMID 38836107, 2024). "Overall, preliminary evidence suggests that pre-existing maternal metabolic disease may alter prolactin dynamics in pregnancy and postpartum." (PMID 36769162, 2023).
metabolic disease (continued). "During postpartum, lactation difficulties in women with metabolic disease present before pregnancy are well-described, but the relationship to prolactin remains unclear." (PMID 36769162, 2023). "Because maternal milk regulates microbiota composition and adequate microbiota protect against the development of metabolic diseases, we aimed to investigate whether PRL/PRL receptor signaling regulates gut microbiota composition in newborn mice at weaning." (PMID 37571383, 2023). "Given that PRL plays critical roles in both lactogenesis and pregnancy metabolism, and considering the prevalence of pregestational metabolic disease in mothers entering pregnancy, the influence of such conditions on PRL secretion and dynamics warrants further exploration." (PMID 36769162, 2023). "Finally, we discuss the possibility of using drugs elevating PRL for the treatment of metabolic diseases." (PMID 36213259, 2022). "In fact, there may even be a role for prolactin enhancing drugs in the treatment of metabolic disease." (PMID 36246929, 2022). "Also, a careful evaluation of drugs that elevate PRL levels is needed in the context of metabolic diseases." (PMID 36213259, 2022). "This is attributed to the interference of work on physiological processes such as the circadian rhythm, leading to changes in the secretion of melatonin, growth hormone, prolactin, leptin and glucocorticoids, leading to weight gain and the onset of metabolic disorders." (PMID 33688327, 2021). "However, an updated review suggests that HomeoFIT PRL within 7–100 μg/L could prevent metabolic disease development, whereas too‐low and too‐high PRL levels are associated with an increased prevalence of metabolic diseases." (PMID 39663784, 2024). "Since maternal milk is a key regulator of gut microbiota composition and microbiota protect against the development of metabolic diseases, in this work, we investigated whether PRL/PRL receptor signaling regulates gut microbiota composition in newborn mice at the end of lactation." (PMID 37571383, 2023). "Therefore, PRL in maternal milk favors metabolic homeostasis in offspring, whereas a lack of adequate PRL actions derived from an obesogenic environment contribute to the development of metabolic diseases." (PMID 37571383, 2023). "Future studies will better clarify the role and the burden of PRL excess or deficiency on metabolic alterations, also investigating the potential role of PRL as a therapeutic target for non-hyperprolactinemic subjects suffering from metabolic diseases." (PMID 36237192, 2022). "Thus, the relationship between PRL and metabolic disorders is complex and varies depending on whether serum PRL is within or outside the physiological range." (PMID 35222274, 2022). "In summary, our findings point to a relative lack of high-quality recent data examining maternal PRL levels—both during pregnancy and postpartum—in women with pregestational metabolic disease (T1DM, T2DM, and PCOS)." (PMID 36769162, 2023). "Furthermore, PRL, CORT, and metabolite parameter levels can also serve for early diagnosis and prognosis of blood changes due to metabolic disorders during these physiological stages." (PMID 34840462, 2021). "The main findings of this study were that co-prescribing aripiprazole not only had no clinical value in reducing PRL levels in the target population of our study but also increased the severity of metabolic disorders compared to the clinical subgroup without co-prescribing aripiprazole." (PMID 36816406, 2023). "However, the long-term use of antipsychotic medications may lead to a large quantity of adverse reactions, such as the extrapyramidal reaction in the nervous system, leucopenia in the blood system, and Prolactin (PRL) and metabolic disorders in the endocrine system." (PMID 29317896, 2017).
cardiovascular disease (24 papers, 2011 to 2025). "Prolactin, secreted from anterior pituitary gland and meanwhile also synthesized by various immune system cells, has been reported to cause a tendency to the cardiovascular diseases." (PMID 21331754, 2011). "This review will enable researchers to better understand the role of PRL/vasoinhibins in cardiovascular diseases." (PMID 35923071, 2023). "This was the first meta-analysis to present the gonadal hormone and PRL values of HD women, which exhibited the function of reproductive system of HD women to some extent and gave us clues for risks estimation of cardiovascular disease, survival and so on." (PMID 37749539, 2023). "In addition to clinical studies, the pathological mechanism of PRL affecting cardiovascular diseases has been explored in in vivo and in vitro studies." (PMID 35923071, 2023). "In addition to the structure, secretion regulation, and signal transduction of PRL/vasoinhibins, this review focuses on the pathological mechanism and clinical significance of PRL/vasoinhibins in cardiovascular diseases." (PMID 35923071, 2023). "The roles of PRL in cardiovascular disorders are discussed in the following section." (PMID 35923071, 2023). "In the past decade, accumulating evidence showed the roles of PRL in cardiovascular diseases." (PMID 35923071, 2023). "Despite GALNT16 being classified as an N‐acetylgalactosaminyltransferase, previous studies have implicated it in protein and lipid metabolism, as well as in AMPK, prolactin, and insulin/IGF signaling pathways, and it may also play a role in lipid metabolism associated with cardiovascular diseases." (PMID 41322030, 2025).
endocrine disorders (24 papers, 2008 to 2025). "This diversity of signaling pathways corresponds to the numerous functions of PRL, which are associated with both physiological states and play important roles in the pathomechanism of diseases, especially endocrine disorders." (PMID 38396659, 2024). "Seventeen studies excluded participants with other endocrine disease and elevated serum prolactin (PRL)." (PMID 29178904, 2017). "However, overexpression of prolactin results in endocrine disorders, which affects normal reproductive function." (PMID 32894113, 2020). "Patients with persistently high prolactin levels of unknown etiology should undergo evaluation for endocrine disorders (strong recommendation; evidence level: Grade A)." (PMID 30736442, 2019). "Additionally, it is uncommon to report post-radiotherapy PRL elevation as a new HP-axis endocrinopathy, as this is unlikely to cause symptoms or require intervention." (PMID 24782984, 2014). "Endocrinopathy (mild increase in TSH and prolactin) was found in only a patient treated with RT alone." (PMID 32787805, 2020). "We screened patients for other endocrine disorders usually related to MEN 1, but with no additional abnormal findings as shown by normal pituitary and adrenal CT scan, normal level of prolactin and clinical data." (PMID 20108468, 2008).
psychiatric disorder (24 papers, 2004 to 2025). A disorder characterized by behavioral and/or psychological abnormalities, often accompanied by physical symptoms. "The results indicate that the combination of DDI, homocysteine and prolactin has a good predictive performance for the incidence of VTE in patients with mental illness." (PMID 38827445, 2024). "As a part of the PFC, the PrL is located in a shallow cortical position and is closely related to the pathogenesis of psychiatric disorders." (PMID 35909449, 2022). "As principal output neurons to subcortical mPFC regions, L5 pyramidal neurons in the PrL reportedly contribute to the development of psychiatric disorders." (PMID 35058738, 2021). "Importantly, analyses restricting the cohort to patients with a history of severe mental illness and analyses comparing prolactin elevating and prolactin-sparing antipsychotics all revealed null associations." (PMID 32831062, 2020). "Moreover, in analyses in patients with a history of severe mental illness results where attenuated towards the null, including for prolactin-elevating antipsychotics (HRadj, 0.86 95%CI 0.44, 1.68), suggesting our overall results are likely influenced by confounding by indication." (PMID 32831062, 2020). "These drugs are very effective in the treatment of psychiatric diseases and do not significantly interfere with prolactin secretion." (PMID 31202268, 2019).
movement disorder (11 papers, 2006 to 2024). Neurological conditions resulting in abnormal voluntary or involuntary movement, which may impact the speed, fluency, quality and ease of movement. "The results of this study showed that ICV injection of prolactin 30 min after ICH improved movement disorders in rats." (PMID 35432801, 2021). "The most increase in the NDS score and the therapeutic effects on the improvement of movement disorders were observed in the treated group with 1 μg/2 μl dose of prolactin." (PMID 35432801, 2021). "Despite widespread use, low price, and no clear differences in effectiveness compared to those of other SGAs risperidone produces more movement disorders and prolactin increase than do other SGAs." (PMID 34135752, 2021). "According to the results of the present study, in cases with ICH, ICV injection of prolactin increased PRL receptor expression in the affected regions, and increased GFAP and APOE genes expression, and caused improved movement disorders in rats." (PMID 35432801, 2021). "Long-term treatment with lurasidone was associated with no clinically meaningful changes in movement disorder scales and with minimal effects on weight, metabolic parameters, and prolactin." (PMID 39020362, 2024). "However, each drug has well-known adverse effects, including weight gain, elevated prolactin levels, sedation, drug-induced movement disorders, and effects on heart rate, blood pressure, and electrocardiograms." (PMID 36467740, 2022). "Therefore, prolactin injected into the ventricles of the brain can greatly reduce ICH-induced movement disorders." (PMID 35432801, 2021). "According to the results, prolactin reduces movement disorders." (PMID 35432801, 2021). "To date, no study has been performed on the therapeutic effects of prolactin in the improvement of movement disorders caused by ICH." (PMID 35432801, 2021). "Because the marker of astrocyte activity is the GFAP gene, an increase in GFAP is associated with an increase in astrocyte activity, so by these results, prolactin may have exerted its protective effects on the improvement of movement disorders by acting on astrocytes in the affected regions." (PMID 35432801, 2021). "In the present study, ICV injection of prolactin increased APOE expression in the affected regions, and movement disorders improved." (PMID 35432801, 2021). "While certain safety issues are often cited as limiting factors for patient acceptability, neither movement disorders measures nor prolactin elevation was predictive of medication satisfaction." (PMID 17054789, 2006). "Thus, ICV injection of prolactin may increase PRL receptor expression in the affected regions, and then due to the astrocytes activated in the damaged regions reduce neurodegeneration, resulting in greatly improved movement disorders." (PMID 35432801, 2021).
immune dysfunction (9 papers, 1997 to 2025). "Alcohol-related problems include immune dysfunction as a result of disturbances in cortisol, testosterone, GH, and prolactin; reproductive problems; cardiovascular abnormalities stemming from disrupted glucose and lipid balance; and bone disease, among others." (PMID 15706763, 1997). "Previous study has demonstrated that PRL level may elevate proinflammatory immune responses, and thus playing an important role in immune dysfunctions." (PMID 40385473, 2025). "This panel might be used to identify the clinically-relevant immune disorders in PRL patients." (PMID 34122414, 2021). "Our findings are consistent with the observation that both PRL and PRL receptor knockout mice do not feature substantial immune dysfunction." (PMID 26553024, 2015).
pituitary gland (8 papers, 2004 to 2025). "The ectopic secretion of hormones like PRL by non-endocrine neoplasms is well recognized and used as therapeutic monitoring." (PMID 15617576, 2004).
neurological disorders (7 papers, 2012 to 2023). "Like oxytocin, prolactin is another pituitary hormone associated with immune system regulation, and it has been implicated in various neurological disorders, including AD." (PMID 36389068, 2022). "Finally, our results highlight the potentiality of PRL as a useful molecule for the treatment of neurodegenerative conditions and neurological diseases." (PMID 28475602, 2017). "In addition, prolactin can regulate oligodendrocyte precursor cells proliferation and promote intrinsic myelin repair, and may have potential for the treatment of neurological disorders." (PMID 22606226, 2012).
benign tumors (6 papers, 2017 to 2026). "A multivariate model including five proteins (CA125, osteopontin, HE4, leptin, and PRL) was found to have an AUC value of 0.996, outperforming CA125 alone; however, only 25 patients with benign tumors and 18 patients with OC were analyzed in this study." (PMID 40502685, 2025).
heart disease (6 papers, 2013 to 2024). "Disturbances of the prolactin/vasoinhibin axis are associated with the pathogenesis of retinal and cardiac diseases and with diseases occurring during pregnancy." (PMID 26310939, 2015).
inflammation (5 papers, 2019 to 2025). Aberrant reaction of the microcirculation characterized by movement of fluid and leukocytes from the blood into extravascular tissues. "However, PRL does not show advantages in prediction of liver inflammation compared to APRI, FIB-4, and GPR." (PMID 33937406, 2021).
neurodegenerative disease (5 papers, 2012 to 2025). A disorder of the central nervous system characterized by gradual and progressive loss of neural tissue and neurologic function. "This study underscores the therapeutic potential of prolactin in attenuating oxidative stress and suggests a possible role in the treatment of neurodegenerative diseases." (PMID 39499702, 2024). "Future studies are warranted to evaluate the efficacy of this non-invasive route for delivering PRL in other neurodegenerative disease models and, ultimately, in humans." (PMID 39499702, 2024). "According to an earlier study, prolactin levels are decreased in many neurodegenerative diseases." (PMID 40471493, 2025). "Overall, the current results suggest that PRL could be of potential therapeutic advantage in the treatment of neurodegenerative diseases." (PMID 28475602, 2017). "in this study, we have identified PRL as one such factor that may play an important role in activating the endogenous hippocampal precursors in cases of neurodegenerative disease." (PMID 22973440, 2012).
adenocarcinoma (4 papers, 1976 to 2023). A common cancer characterized by the presence of malignant glandular cells. "PRL immunolabelling was only positive in two out of the four adenocarcinomas, specifically in neoplastic mammary epithelial cells located in heterogeneous clusters." (PMID 37626804, 2023). "Plasma prolactin (PRL) and carcinoembryonic antigen (CEA) were measured by radioimmunoassay in 74 patients with adenocarcinoma of colon and rectum." (PMID 1419646, 1992).
bacterial infection (2 papers, 2023 to 2024). "This study aimed to determine the nature of the distribution of relative frequencies of alleles and genotypes of polymorphic PRL and NOS2 in Holstein cows and to identify the relationship of polymorphisms with resistance to viral and bacterial infections." (PMID 36855359, 2023). "DNA amplification of Holstein cattle for the polymorphic regions of PRL and NOS2 using the PCR-RFLP method revealed a possible connection between the distribution of relative allele frequencies of bPRL and bNOS2 and resistance to viral and bacterial infections." (PMID 36855359, 2023). "Interestingly, we also show that LPS promotes enhanced PRL expression in JEG-3 cells and PRL-receptor expression in decidual macrophages, suggesting that PRL elevation may be a potential biomarker for bacterial infection at the placenta." (PMID 39763651, 2024).